TGM2 (transglutaminase 2)
Diseases named in the same sentence as TGM2 in open-access papers (continued):
Sharing a sentence is not in itself a finding about the gene and the disease.
gastric cancer (11 papers, 2010 to 2025). A primary or metastatic malignant neoplasm involving the stomach. "For instance, transglutaminase-2 (TGM2) and neuro oncological ventral antigen 2 (NOVA2) have been implicated in poor prognosis for gastric cancer patients." (PMID 40248695, 2025). "Sung-Yup Cho at Seoul National University College of Medicine, Korea and co-workers measured copy numbers and expression levels of TGM2 in gastric cancer cell lines and in tissue samples from patients undergoing gastrectomy." (PMID 32467608, 2020). "TGM2 has been shown to be related to hypoxia and HIF1α in malignant pleural mesothelioma and gastric cancer." (PMID 32765489, 2020). "For example, in gastric cancer, through a GTPase manner, TGM2 inhibits tripartite motif-containing protein 21 (TRIM21)-mediated ubiquitination and degradation of signal transducer and activator of transcription 1 (STAT1), and thus enhances its stability and oncogenic actions." (PMID 39115570, 2024). "In addition, stomach cancer patients with higher expression of TGM2 had poorer prognoses, indicating the potential therapeutic value of targeting this enzyme." (PMID 32467608, 2020). "Recent studies have confirmed that TGM2 induces EMT and thus may contribute to acquired drug resistance in colon, breast, and gastric cancer cells; and increased expression of TGM2 appears to drive glycolytic metabolism in cells of breast and renal cancers." (PMID 30393774, 2018). "Here, we investigated a novel role for transglutaminase 2 (TGM2) in the development of tumor-promoting inflammation and recruitment of TAMs to gastric cancer (GC) tissues." (PMID 32467608, 2020). "Another study on gastric cancer (GC) also suggest that TGM2 might provide a new target for the diagnosis and treatment of GC." (PMID 31877708, 2019).
Obesity (11 papers, 2015 to 2024). Accumulation of substantial excess body fat. "For example, a study found that loss of TGM2 sensitizes for diet-induced obesity-related inflammation and insulin resistance." (PMID 36824360, 2023). "Our data suggest that lipotoxicity, a typical feature of obesity-associated T2D, reduces LncTGM2, which in turn provokes a reduction of TGM2 in pancreatic beta cells." (PMID 36824360, 2023). "In this sense, several studies have described a link between TGM2 and obesity and associated glycemic traits." (PMID 36824360, 2023). "Defects in TGM2 gene are associated with early onset of Type 2 diabetes, and TNF-alpha has been implicated as a causative factor in obesity-associated insulin resistance and the pathogenesis of type 2 diabetes." (PMID 26302420, 2015). "Despite robust data from mouse studies linking TG2 to adipose tissue function in obesity, TGM2 showed no altered expression between the Heavy–Lean co-twins." (PMID 33167412, 2020).
prostate carcinoma (11 papers, 2007 to 2025). A carcinoma that arises from epithelial cells of the prostate gland. "Alternative splicing of TGM2 occurs differently in cancer cell lines, and in prostate cancer cells the alternative splicing of TG2 is a more active process." (PMID 31360119, 2019). "TGM2 expression is shown to negatively regulate AR expression and to attenuate androgen sensitivity of prostate cancer cells." (PMID 27447616, 2016). "This suggests that TGM2-regulated inflammatory signaling may contribute to the androgen dependence of prostate cancer cells." (PMID 27447616, 2016). "Thus, TGM2 is concluded as a cancer stem cell survival factor in various types of cancers, including prostate cancer." (PMID 27447616, 2016). "This study indicates that TGM2-knockdown in benign prostate epithelial cells can reduce cell growth and migration in a CAF-dependent manner, warranting further investigation of TGM2′s regulation and role in prostate cancer initiation and progression." (PMID 36765657, 2023). "However, a role for TGM2 in prostate cancer development and progression has not been demonstrated." (PMID 36765657, 2023). "Even though no direct androgen regulation has been reported for the TGM2 gene, another transglutaminase enzyme (TGM4) has been found to be androgen regulated in human prostate cancer cell lines." (PMID 17553164, 2007).
type 2 diabetes (11 papers, 2013 to 2024). "The damaging p.Met330Arg nsSNV is among the three reported heterozygous missense mutations in the TGM2 gene associated with early-onset type 2 diabetes in a small disease cohort." (PMID 28248968, 2017). "Missense mutations in the TGM2 gene encoding transglutaminase 2 are found in patients with early-onset type 2 diabetes, but little reports found the relation between TGM2 and RA." (PMID 26252209, 2015). "Transglutaminase type 2 (TG2) has been reported to be a candidate gene for MODY, with three types of missense mutations found in the TG2-encoding gene (TGM2) in 3 families with early-onset Type 2 diabetes." (PMID 23717413, 2013). "Three different missense mutations (M330R, I331N, N333S) that impair transamidase activity have been found in TGM2 in 3 families with early-onset Type 2 diabetes." (PMID 23717413, 2013). "It is important to note that TGM2, TGM3, and TGM7 nsSNVs do not seem to be associated with any pathological phenotype except perhaps TGM2 heterozygous mutations associated with early-onset type 2 diabetes, an observation which has not been confirmed in animal experiments and large clinical cohorts." (PMID 28248968, 2017). "Moreover, based on the T2D knowledge portal, the genomic region in which LncTGM2 is located (also containing TGM2, RPRD1B and KIAA1755 genes) has been associated with several metabolic and glycemic traits, including cardiovascular disease related parameters, cholesterol and type 2 diabetes." (PMID 36824360, 2023).
cystic fibrosis (10 papers, 2012 to 2021). Autosomal recessive disorder caused by pathogenic variants in the CFTR gene (cystic fibrosis transmembrane conductance regulator), which encodes a chloride and bicarbonate channel expressed in epithelial cells, and follow the diagnosis criteria. "CF is characterized by mutations in cystic fibrosis transmembrane conductance regulator (CFTR), a chloride channel whose malfunction triggers the activation of transglutaminase-2 (TGM2), as well as the inactivation of the Beclin-1 (BECN1) complex resulting in disabled autophagy." (PMID 31321000, 2019).
osteoporosis (10 papers, 2015 to 2025). A condition of reduced bone mass, with decreased cortical thickness and a decrease in the number and size of the trabeculae of cancellous bone (but normal chemical composition), resulting in increased fracture incidence. "For example, allosteric activation of transglutaminase 2 regulates osteoblast differentiation by promoting mitochondrial elongation and increasing ATP production, which ameliorates osteoporosis in ovariectomized mice." (PMID 41331010, 2025). "Taken together, these findings show a previously undescribed pharmacological allosteric site on TGM2 for osteoporosis treatment, and also provide an available chemical tool for interrogating TGM2 biology and developing bone anabolic agent." (PMID 37088726, 2023). "We also systematically explored the interactome of TGM2 for interrogating the mitochondrial energy generation mechanism in osteoblast differentiation and proved anti‐osteoporosis effect of FSK in vivo." (PMID 37088726, 2023). "Here, TGM2 was identified as a crucial cellular target of FSK for osteoblast differentiation, which provides a potential direction to deplore new drug candidate for osteoporosis." (PMID 37088726, 2023). "For example, Ostf1 (osteoclast stimulation factor 1) can promote osteoporosis, Tgm2 is involved in negative artery remodeling, and IGF2 can contribute to senescence of MSCs." (PMID 32727501, 2020).
anemia (9 papers, 2015 to 2026). A reduction in the number of red blood cells, the amount of hemoglobin, and/or the volume of packed red blood cells. "TGM2 knockout mice exhibit mild anemia with reduced RBC counts and hematocrit, indicating that TGM2 may be involved in erythropoiesis." (PMID 37169024, 2023).
diabetic nephropathy (9 papers, 2017 to 2025). "In human patients with CKD where glomerular scarring is a common histopathological feature, such as in diabetic nephropathy, a significant correlation between transglutaminase 2 (TG2) and fibrosis in both the tubulointerstitial and glomerular space has been demonstrated." (PMID 40727272, 2025).
renal carcinoma (9 papers, 2016 to 2025). A carcinoma arising from the epithelium of the renal parenchyma or the renal pelvis. "In renal cancer, CHIP targets transglutaminase 2 (TG2), a negative regulator of VHL." (PMID 34831344, 2021).
epilepsy (8 papers, 2019 to 2025). A brain disorder characterized by episodes of abnormally increased neuronal discharge resulting in transient episodes of sensory or motor neurological dysfunction, or psychic dysfunction. "To investigate the role of TGM2 in epilepsy, we evaluated its expression changes and functional implications using both in vitro and in vivo models." (PMID 41456951, 2025). "This identifies a novel molecular pathway where TGM2 links microglial function to synaptic remodeling in epilepsy, offering a new potential therapeutic target." (PMID 41456951, 2025). "Collectively, these findings establish TGM2 as a critical protective factor against epilepsy, highlighting its potential as a therapeutic target for intervention." (PMID 41456951, 2025). "Although the present study established TGM2 as a critical regulator of microglial function and synaptic remodeling in epilepsy, several questions remain." (PMID 41456951, 2025). "In the current epilepsy model, Golgi staining revealed reduced dendritic spine density following TGM2." (PMID 41456951, 2025). "Collectively, these results demonstrated that the epilepsy model induced TGM2 overexpression and subsequent colocalization in microglia." (PMID 41456951, 2025). "In mouse models of epilepsy, the current study measured significantly elevated TGM2 expression levels in the hippocampus and cortex and showed enhanced colocalization of TGM2 with microglia in hippocampal regions." (PMID 41456951, 2025). "However, the roles and mechanisms of TGM2 in microglial‐mediated synaptic phagocytosis, as well as its contribution to sustained neuronal excitability in epilepsy, remain understudied." (PMID 41456951, 2025). "Moreover, the epilepsy kindling rate was lower in the TGM2 overexpression group than in the control group, whereas TGM2 knockdown increased kindling rate (p < 0.01)." (PMID 41456951, 2025). "Functionally, TGM2 expression levels inversely correlated with epilepsy severity." (PMID 41456951, 2025). "These key findings suggest that TGM2 may regulate the microglial functions involved in the pathological progression of epilepsy." (PMID 41456951, 2025). "TGM2 was revealed as an intrinsic neuroprotective factor in epilepsy." (PMID 41456951, 2025). "In neural tissues, TGM2 localizes to the brain, spinal cord, and peripheral nerves; however, its distribution in brain regions relevant to epilepsy (hippocampus and cortex) remains unclear." (PMID 41456951, 2025). "TGM2 is a calcium‐dependent acyltransferase, and previous studies have demonstrated its involvement in apoptosis, inflammatory responses, and protein cross‐linking; however, its regulatory role in glial cell function in epilepsy was previously unknown." (PMID 41456951, 2025). "Specifically, viral‐mediated TGM2 overexpression (AAV‐Tgm2) and knockdown (shTgm2) models were established, and TGM2 overexpression prolonged the latency period and reduced the frequency of seizures, whereas TGM2 knockdown exacerbated epilepsy progression." (PMID 41456951, 2025).
glaucoma (8 papers, 2012 to 2025). Increased pressure in the eyeball due to obstruction of the outflow of aqueous humor. "Further, LOX, LOXLs and TGM2 do have their place in glaucoma; single-nucleotide polymorphism in LOXL1 has been implicated in exfoliation glaucoma." (PMID 32973273, 2020). "In addition, elevated levels of TGM2 are implicated in ocular diseases, such as DED and glaucoma, where negative regulation of monomeric lacritin by TGM2 could be an underlying mechanism." (PMID 40784456, 2025).
leukemia (8 papers, 2014 to 2024). A malignant (clonal) hematologic disorder, involving hematopoietic stem cells and characterized by the presence of primitive or atypical myeloid or lymphoid cells in the bone marrow and the blood. "Some other downregulated genes are related to chemo-resistant or leukemia aggressiveness such as Thbs1, Tgm2, Ambp, and the AF9 regulator Sgk1, which negatively regulates the DOT1A-AF9 repressor complex." (PMID 28974232, 2017).
mantle cell lymphoma (8 papers, 2012 to 2025). Mantle cell lymphoma is a rare form of malignant non-Hodgkin lymphoma affecting B lymphocytes in the lymph nodes in a region called the ``mantle zone''. "Another mechanism that has been proposed is the interaction of TGM2 with NF-κB, with the latter regulating autophagy induction in mantle cell lymphoma." (PMID 37232732, 2023). "TG2, an enzyme encoded by the TGM2 gene, a stress-responsive gene, is associated with NF-kB expression, and its up-regulation is correlated with poor prognosis in mantle cell lymphoma (MCL) patients." (PMID 34782660, 2021). "In a previous study, a positive regulatory loop was found among TGM2 (TG2)-NF-ĸB/NF-κB signaling, IL-6, and autophagy in cancer, as exemplified by mantle cell lymphoma as the model system in that study." (PMID 39654623, 2024).
pulmonary arterial hypertension (8 papers, 2011 to 2024). Pulmonary arterial hypertension (PAH) is a group of diseases characterized by mean pulmonary artery pressure >20 mmHg and elevated pulmonary arterial resistance leading to right heart failure. "Tgm2 could also promote pulmonary hypertension by other means that may affect receptor levels by altering ubiquitination or influence the presence of auto-antibodies." (PMID 29910735, 2018). "Due to the upregulation of TGM2 in pulmonary arterial smooth muscle cells during pulmonary arterial hypertension (PAH), the serotonylation of Akt may play a role in the remodeling of pulmonary arteries in this disease." (PMID 39254383, 2024).
Iron deficiency anemia (7 papers, 2016 to 2026). "Individuals with unexplained iron deficiency should also be tested for Tissue Transglutaminase (TTG) antibodies, particularly anti-transglutaminase-2 antibodies, provided they have not been excluding gluten from their diet for at least six weeks." (PMID 40320333, 2025).
lymphoma (7 papers, 2014 to 2025). A malignant (clonal) proliferation of B- lymphocytes or T- lymphocytes which involves the lymph nodes, bone marrow and/or extranodal sites. "The expression pattern of cathepsin D and TGM2 suggested that they are not expressed by lymphoma cells, but rather macrophages." (PMID 25362242, 2014).
squamous cell carcinoma (7 papers, 2011 to 2023). A carcinoma arising from squamous epithelial cells. "Interestingly, the expression of some of those genes (TGM2, BNIP3, FIS1) has been linked as prognostic markers in squamous cell carcinomas." (PMID 38201216, 2023).
viral infection (7 papers, 2012 to 2023). "Although we could not find a direct effect of OPN on TGM2 formation, the current findings led us to speculate that viral infection and aging may stimulate TGM2 polymerization, which further enhances collagen binding." (PMID 32009132, 2020). "TG2 level of expression is sensitive to changes in physiological conditions, since the TGM2 gene (which encodes for TG2), is regulated by several agents and stimuli, like apoptotic signals, viral infections, ER stress, hypoxia, inflammation, and cancer-activated pathways." (PMID 37898636, 2023). "Indeed, the knockdown of DUSP1 or the m6A eraser ALKBH5 enhanced the expression of innate immune response genes, including IL-1β, CSF3, TGM2, and SRC, during bacterial or viral infections." (PMID 36625590, 2023).
allergic asthma (6 papers, 2013 to 2024). A asthma with a basis in a pathological type I hypersensitivity reaction. "Transglutaminase 2 (TG2), a multifunctional calcium‐dependent acyltransferase, is upregulated in asthmatic airways and reported to play a role in the pathogenesis of allergic asthma." (PMID 33945658, 2021). "In addition, the same findings are observed in allergic asthma of normal mice when treated with the TGM2 inhibitor (Cysteamine)." (PMID 32024540, 2020). "Also, we recommend selective suppression of pathogenic M2a proteins e.g. TGM2, CCL17/CCL22, TGF-β1, and murine Arg1, FIZZ1 and CHI3L3, for the future developments of effective therapies for allergic asthma." (PMID 32024540, 2020).
Ataxia (6 papers, 2010 to 2024). Ataxia refers to impaired coordination of voluntary muscle movement. "Our findings support a model where the elevated levels of spermine and increased polyamination of target proteins such as α-Synuclein by TGM2 in Smox/Sat1-dKO Purkinje cells drive the development and progression of ataxia." (PMID 33054763, 2020). "Finally, there were clear roles of transglutaminase-2 (TGM2) in the cerebellar pathologies manifest in Smox/Sat1-dKO mice, as pharmacological inhibition of transglutaminases reduced the severity of ataxia and cerebellar injury in Smox/Sat1-dKO mice." (PMID 33054763, 2020). "Based on our results, we propose that prolonged deficits in polyamine catabolism, increased TGM2 activity, and enhanced α-Synuclein expression, polyamination, and aggregation result in the activation of a circuit that leads to cerebellar injury and ataxia in Smox/Sat1-dKO mice." (PMID 33054763, 2020).
cervical carcinoma (6 papers, 2014 to 2023). A carcinoma arising from either the exocervical squamous epithelium or the endocervical glandular epithelium. "Furthermore, the expressions of S100P, S100A4, KRT7 and TGM2 were also induced by silencing of ACTL6A in cervical cancer cells." (PMID 34395295, 2021). "This suggested that the enhanced expression of TGM2 is, at least in part, responsible for the enhanced migration of cervical cancer cells, lacking Caspase-8 expression." (PMID 36399280, 2022). "The mean levels of CNOT7, PAX5, and SPDEF are slightly elevated in CESC samples compared with those in healthy tissue, though not significantly, while the level of TGM2 is significantly downregulated in cervical cancer." (PMID 30918060, 2019). "In light of these findings, we could show that the knock-down of TGM2 expression dramatically decreased the ability of cervical cancer cells lacking Caspase-8 expression to migrate." (PMID 36399280, 2022). "Additionally, concurrently with the patient data, transcriptome and proteomic profiling of Caspase-8-depleted cervical cancer cell lines (HeLa and SiHa) identified numerous genes with altered expression, including STOM and TGM2, which may boost the propensity for metastasis and invasion." (PMID 36399280, 2022).
Crohn disease (6 papers, 2013 to 2022). A gastrointestinal disorder characterized by chronic inflammation involving all layers of the intestinal wall, noncaseating granulomas affecting the intestinal wall and regional lymph nodes, and transmural fibrosis. "In agreement with our results, however, studies on Crohn’s disease patients have reported an inverse relationship between TGM2 and disease activity." (PMID 32458144, 2020).